AKR1B10 (aldo-keto reductase family 1 member B10)
Diseases named in the same sentence as AKR1B10 in open-access papers (continued):
Sharing a sentence is not in itself a finding about the gene and the disease.
cancer (continued). "AKR1B10 protein expression levels of AKR1B10 (evaluation scores) in the cancer tissue were higher than that in para-carcinoma tissue in 24/25 cases." (PMID 28402270, 2017). "AKR1B10 is expressed at different levels in different human cancer cells, affecting the growth and survival of tumors, and its activity is closely related to tumor development." (PMID 26949513, 2016). "In comparison with normal tissues, AKR1B10 is considerably overexpressed in several types of cancer such as hepatocellular, lung, breast, gastric and pancreatic." (PMID 27635343, 2016). "It is very interesting that AKR1B10 expression shows an opposite pattern in digestive tract cancers compared with cancers arising outside of the digestive tracts." (PMID 26949513, 2016). "In the present study, we have found that both AKR1B10 protein and mRNA levels were reduced in most of NPC tumors compared with para-carcinoma and benign tissues, which further suggests that AKR1B10 expression is down-regulated in the digestive tract cancers." (PMID 26949513, 2016). "While AKR1B10 is a well characterized enzyme with high retinaldehyde reductase activity, involved in the development of several cancer types, the enzymatic activity and physiological role of AKR1B15 are still poorly known." (PMID 26222439, 2015). "Another member, AKR1B10, is normally expressed in adrenal gland and small intestine, and induced in several types of cancer, such as non-small cell lung carcinoma and hepatoma." (PMID 26222439, 2015). "AKR1B10 was shown to be downregulated using small, interfering, RNA-inhibited cancer cell proliferation both in vitro and in vivo." (PMID 24747592, 2014). "The expression of some genes, such as ALDH3A1, TNS4, CLDN2, and AKR1B10, which are known to play important roles in cancer cell migration, invasion, proliferation and apoptosis, were increased in HCT-8 R cells." (PMID 24884630, 2014). "Five enzymes (LDHB, MDH2, PKM2, AKR1B1, and AKR1B10) out of 40 enzymes in pyruvate metabolism pathway are overexpressed in cancer." (PMID 25243088, 2014). "Many studies have demonstrated AKR1B10 upregulation in several types of cancer, including several recent reports on HCC." (PMID 24747592, 2014). "The article by Laffin and Petrash (2012) examines the expression of AKR1B1 and AKR1B10 across all major human cancer types." (PMID 23734127, 2013). "For instance, AKR1B10 may interact with glyceraldehyde-3-phosphate dehydrogenase to reduce autophagy by modifying its reductase activity in cancer cells." (PMID 39744163, 2025). "Results indicated that AKR1B10 was highly expressed in the gastrointestinal tract in health donors, but the expression of AKR1B10 was significantly changed in most of cancer types, which may be ascribed to DNA methylation in its promoter." (PMID 39712017, 2024). "Clinical research has largely focused on AKR1B1 and AKR1B10 with very little emphasis on other members that could shed light on specific pathways and cellular processes that are specific to cancer type and tissue of origin." (PMID 39055885, 2024). "We further explored AKR1B10 function in pan-cancer cells through GSEA." (PMID 39712017, 2024). "Overexpression of AKR1B10 has been identified in smoking-related cancers, such as lung cancer." (PMID 39737179, 2024). "A comprehensive analysis of AKR1B10 in pan-cancers is certainly warranted." (PMID 39712017, 2024). "AKR1B10 may promote cancer progression through fatty acid synthesis, but prevent cancer via regulating autophagy and FGF1." (PMID 39712017, 2024). "Therefore, accumulating evidence supports AKR1B10 as a potential target for cancer diagnosis and treatment." (PMID 39001490, 2024). "AKR1B10 expression is significantly altered in various types of cancers." (PMID 39712017, 2024). "These differential roles of AKR1B10 in different types of cancers may be ascribed to the intrinsic context of organs, rather than to its biological functions." (PMID 38370384, 2024).
cancer (continued). "Recent research suggests that AKR1B10 may play a crucial role in the initiation and progression of various cancers." (PMID 38931461, 2024). "Mutation analysis indicated that scatter missense mutations, nonsense mutations, frame shift inserts, frame shift deletions and splice sites were observed within the coding sequence of AKR1B10 in 17/33 cancers, of which UCEC had the highest incidence rate of 3.4%." (PMID 39712017, 2024). "Taken together, epigenetic might contribute more to the alteration of AKR1B10 expression in pan-cancer." (PMID 39712017, 2024). "The TIMER database was utilized to observe AKR1B10 expression levels across various cancer types." (PMID 38802416, 2024). "Therefore, the up-regulation of AKR1B10 is believed to play a key role in promoting the tumor phenotype of cancer cells." (PMID 36845547, 2023). "Moreover, given its role in detoxification, AKR1B10 was shown to contribute to the chemoresistance acquisition against some anti-cancer drugs, such as daunorubicin, and idarubicin, and cisplatin." (PMID 36845547, 2023). "Fourth, AKR1B10 is thought to contribute to chemoresistance in various cancers." (PMID 36661656, 2022). "AKR1B10 expression in cancer tissues was confirmed by RT-PCR and Western blot." (PMID 35280770, 2022). "Furthermore, experimental results in vitro and in vivo demonstrated that AKR1B10 is involved in cancer cell proliferation." (PMID 36584078, 2022). "Expression of AKR1B10 was further evaluated in cancer tissues with immunohistochemistry (IHC)." (PMID 35280770, 2022). "The results of the current study are very promising therefore suggested that both compounds can be used in future for the synthesis of more potential inhibitors of the selected targets, for the treatment of respective cancers caused due to over-expression of AKR1B1 and AKR1B10." (PMID 36301939, 2022). "AKR1B10 has also been reported to have an oncogenic role across different cancer types." (PMID 35820706, 2022). "AKR1B10 is reported to be related with chemoresistance of several cancers." (PMID 35178443, 2022). "AKR1B10 is known to be secreted via the Extracellular Vesicles (EVs) and has been identified as an interactor that favours metastasis growth in an indirect co-culture cancer model." (PMID 35163833, 2022). "Although AKR1B10 is profusely expressed in epithelial tissues of the digestive tract, with a low level in the liver, it has been reported that this enzyme is upregulated in some cancers, including HCC." (PMID 35563425, 2022). "Although epalrestat may be harmful to CRC HCT-8 cells by promoting DNA damage, it enhances the efficacy of sorafenib (an anti-cancer drug) on HCC by inhibiting AKR1B10." (PMID 34063865, 2021). "Several roles have been proposed for AKR1B10 in cancer growth and metastasis." (PMID 34063865, 2021). "Among the five AKRs, AKR1B10 may play a crucial role in acquiring resistance to several anti-cancer drugs." (PMID 34063865, 2021). "AKR1B10 has a very high catalytic efficiency for all-trans-retinaldehyde and a more specific tissue expression (mostly in the gastrointestinal, GI, tract), although it is overexpressed in several cancer types and skin diseases." (PMID 34940623, 2021). "Many studies demonstrated that AKR1B1 and AKR1B10 are involved in different cancers." (PMID 34298614, 2021). "Therefore, utilizing AKR1B10 inhibitors for cancers that highly express AKR1B10 is expected in clinical practice." (PMID 34063865, 2021). "A few studies have shown that AKR1B10 is closely correlated with the progression of cancer." (PMID 34419144, 2021). "Thus, AKR1B10 acts as a double-edged sword depending on the type of cancer cells, and further understanding its role in the onset and progression of these diseases should be pursued." (PMID 34063865, 2021). "AKR1B10 expression levels were searched in multiple cancer types via the GEPIA Platform." (PMID 34552036, 2021). "AKR1B10 expression levels were detected in the NPC tissues obtained before any anti-cancer therapy." (PMID 33767586, 2021).
cancer (continued). "Thus, AKR1B10 is considered a key factor responsible for the development of chemoresistance in these cancer cells." (PMID 34063865, 2021). "Besides, AKR1B10 expression was also reported to upregulate in carboplatin–gemcitabine combination chemotherapy cancer patients." (PMID 34035231, 2021). "Taken together, these data suggested AKR1B10 might function as an oncogene contributing to the cancer progression and clinical poor outcome." (PMID 34035231, 2021). "AKR1B10-positive staining was significantly higher in cancer tissues than normal breast tissues." (PMID 34419144, 2021). "Since aldose reductase (AKR1B1) has a similar structure to AKR1B10 and is involved in glucose and prostaglandin metabolism, developing inhibitors as anti-cancer drugs or adjuvant therapies for chemotherapeutic drug resistance must ensure selective inhibition of AKR1B10." (PMID 34063865, 2021). "Thus, the detoxification of RCS by AKR1B10 is the most critical step in developing resistance to these anti-cancer drugs." (PMID 34063865, 2021). "Aldo-keto reductase B10 (AKR1B10) plays a role in the formation and development of carcinomas." (PMID 33767586, 2021). "These previous investigations revealed that knocking down AKR1B10 expression induces cancer cell apoptosis and inhibited cancer cell proliferation, suggesting AKR1B10 could serve as a potential therapeutic target." (PMID 32097409, 2020). "AKR1B10 has also been shown to promote cancer cell survival by 2 distinct studies." (PMID 32097409, 2020). "Likewise, AKR1B10 inhibition or knockdown by small interfering RNA reduced the proliferation of different cancer cell lines." (PMID 33322571, 2020). "Although the overall accuracy of AKR1B10 expression level in distinction between cancer and healthy lung tissue was 76%, with a specificity of 98%, our results indicated that such marker exhibited low sensitivity, hampering its use for cancer screening such specific setting." (PMID 32097409, 2020). "Lipogenesis plays an important role in carcinogenesis and a number of studies have provided evidence showing that AKR1B10 may contribute to the development and progression of cancer through its relationship with de novo fatty acid synthesis." (PMID 30959792, 2019). "AKR1B10 expression levels during early stage HCC might also be exploited for early cancer detection in those patients with AKR1B10-expressed cells." (PMID 30959792, 2019). "Moreover, AKR1B10 participates in the activation of several mechanisms of drug resistance during the treatment of various cancers." (PMID 30320113, 2018). "Hence, AKR1B10 has not only become a biomarker (as it is upregulated in various types of cancer), but has also turned into an attractive pharmacological target in cancer prevention and treatment." (PMID 30469331, 2018). "AKR1B10 has been previously reported as a potential diagnostic marker specific to smokers' NSCLCs, while USP14 was reported to be over-expressed in various types of cancer, including NSCLC." (PMID 29285267, 2017). "Thus, the exact mechanisms have been always required for exploring the use of AKR1B10 as therapeutic target in cancer clinics." (PMID 28402270, 2017). "It is well known that AKR1B10 knockdown inhibits proliferation of cancer cells." (PMID 26948042, 2016). "As AKR1B10 has been shown to be highly upregulated in other types of cancer, it would be interesting to determine whether, as with mutation of NRF2, increased AKR levels segregate to SCC of tissues other than lung." (PMID 27824809, 2016). "Therefore, we only compare AKR1B10 expression in NPC tissues with that in para-carcinoma tissues in same NPC patients or with that in benign tissues in other patients." (PMID 26949513, 2016). "Additionally, our study suggests that 14-3-3ε-induced AKR1B10 promotes cancer cell proliferation by reducing RA production in the early stages of primary HCC." (PMID 26516929, 2015).
cancer (continued). "Also, tolrestat, which efficiently inhibits AKR1B10, is suggested to have a potential application in cancer control." (PMID 24348813, 2014). "All the examined small compounds demonstrated anticancer activity in the in vitro experiments and may impact cancer cells by acting on AKR1B10, MMP-9 and their targets." (PMID 24348813, 2014). "AKR1B10 has been reported to be upregulated in number of cancers." (PMID 24348813, 2014). "Also aldo-keto reductases AKR1B1 and AKR1B10 enriched in cancer ESTs catalyze reduction of D-glyceraldehyde to glycerol and 2-hydroxypropanal to propane-1,2-diol in glycerolipid metabolism." (PMID 25243088, 2014). "Furthermore, our studies also demonstrated that AKR1B10 mediates ACC1 stability and increase fatty acid synthesis; knockdown of AKR1B10 inhibits cancer cell growth and triggers apoptosis." (PMID 23358327, 2013). "Because AKR1B10 and Akr1b8 are not only detoxifying enzymes but also affect de novo fatty acids synthesis in cancer cells, it would be interesting to determine if and which of the enzymatic activities of AKR1B10 could be involved in adipose tissue homeostasis." (PMID 22876234, 2012). "EAC exhibits the enhanced extracellular matrix remodeling (collagens, IGFBP7, PLAU) effects expected in an aggressive form of cancer, as well as evidence of reduced expression of genes associated with mucosal (MUC6, CA2, TFF1) and xenobiotic (AKR1C2, AKR1B10) defenses." (PMID 21829465, 2011). "However, the role of AKR1B10 in cancer development and progression is complex." (PMID 39712017, 2024). "However, the role of AKR1B10 in different cancers is complex and remains elusive." (PMID 39712017, 2024). "Additionally, AKR1B10 can activate the Erk signaling pathway to affect cancer development." (PMID 36028503, 2022). "Indeed, a previously published work reported that AKR1B10 could be detected in the blood of patients suffering from different forms of cancers." (PMID 35163833, 2022). "AKR1B10 could activate ERK signaling pathway in various cancer cells." (PMID 36028503, 2022). "Therefore, AKR1B10 could play an important role in various aspects of tumor progression and may be a potential therapeutic target for cancer treatment." (PMID 36661656, 2022). "In recent studies, AKR1B10 may be involved in the occurrence, and progression of many cancers." (PMID 34419144, 2021). "In addition, AKR1B10 promotes cancer metastasis through activation of the ERK signaling pathway, which stimulates the downstream integrin α5/δ-catenin mediated FAK/Src/Rac1 signaling pathway and increases the expressions of matrix metalloproteinase-2 (MMP2) and vimentin." (PMID 34063865, 2021). "AKR1B10 may play a role in cancer development and progression through a variety of molecular mechanisms including the detoxification of cytotoxic carbonyls, modulation of retinoic acid levels, and regulating cellular fatty acid synthesis and lipid metabolism 6-8." (PMID 33767586, 2021). "Thus, it is not surprising that aberrantly low level of AKR1B10 in the gastrointestinal tract is closely linked with the development of cancers, as well as inflammatory conditions like diabetic nephropathy." (PMID 32615540, 2020). "Since AKR1B10 overexpression is already detectable in precancerous lesions, metabolic events mediated by this enzyme could play a crucial role in the development of cancer." (PMID 29532688, 2018). "In addition, various studies were revealed that increased expression of AR and AKR1B10 is involved in carcinogenesis and drug resistance, and AR/AKR1B10 inhibitors could be potentially effective drugs for cancer therapeutics." (PMID 28978011, 2017). "In this study, the suppression of ADH4, AKR1B10 and AKR1C2 genes and the subsequent encoded proteins may help to increase the intracellular methylglyoxal level which can subsequently lead to apoptosis in cancer cells." (PMID 27635343, 2016).
cancer (continued). "We noticed that AKR1B10 was enriched with cancer cell features and pathways, as well as apoptosis, cell cycle, autophagy, and ECM interaction processes in some cancers." (PMID 39712017, 2024). "Individual oncogenes (oncogene lists obtained from MSigDB) with a high gain of novel isoforms in the Iso-seq cancer transcriptome were identified; for example, AKR1C2 and AKR1B10 are often overexpressed in HCC and contribute to hepatocarcinogenesis." (PMID 38185659, 2024). "The gene AKR1B10 is typically found in intestinal epithelial cells, but its expression is low in the early stages of CRC and increases as the cancer progresses." (PMID 39737179, 2024). "This study implies that not only does AKR1B10 hinders the nuclear translocation of GAPDH by interacting with it, but it also obstructs the conversion of normal cells to cancer cells by suppressing the downregulation of autophagy through AMPK phosphorylation." (PMID 39737179, 2024). "Epalrestat enhances the chemosensitivity of cancer cells to doxorubicin by inhibiting the activity of AKR1B1 and/or AKR1B10 as well as by preventing epithelial-mesenchymal transition." (PMID 39055885, 2024). "Therefore, a special function of AKR1B10 in an indicated type of cancer may be context-dependent." (PMID 39712017, 2024). "Metabolic enzymes AKR1B10, ALDH3A1, and ALDH1A1 have been reported by our group and others as leading candidate biomarkers for multiple cancer types, including lung." (PMID 37760474, 2023). "EPHX2, ACSF2, CYP27A1, ACSS1, and ALDH1L1 showed hypermethylation in several types of human cancer; on the contrary, AKR1B10, POLG2, NDUFB8, ACACB, and MRPS22 consistently showed hypomethylation in several types of human cancer." (PMID 37223030, 2023). "On the basis of these facts, it can be observed that both AKR1B10 and AKR1B1 are aberrantly expressed in different cancer so there is a need to explore potential inhibitors of both targets." (PMID 36301939, 2022). "It participated in the IRAK4/IRAK1/AP-1/AKR1B10 signaling pathway and AUF1-mediated post-transcriptional regulation of AKR1B10 expression to regulate cancer stemness and drug resistance in HCC." (PMID 36246599, 2022). "To determine the feasibility of AKR1B10 as a biomarker for NRF2 activation across different malignancies, we exploited The Cancer Genome Atlas (TCGA) and Cancer Cell Line Encyclopedia (CCLE) multilevel data." (PMID 36068196, 2022). "The fourth group, which was consistently identified as cancer by SRS images, contained highly expressed OSCC marker genes including GSTP1, AKR1B10, FTH1, and FTL." (PMID 35776767, 2022). "In turn, overexpressed AKR1B10 promotes p-ERK1/2, MMP2, and vimentin expression, which mediate activation of the MAPK signaling pathway, thereby enhancing cancer cell proliferation and invasion in vitro and in vivo." (PMID 35563845, 2022). "AKR1B10, which is overexpressed in NASH, is known to also be overexpressed in cells of several cancer types, including hepatocellular carcinoma and lung cancer." (PMID 35052547, 2021). "Furthermore, we found higher AKR1B10 mRNA levels but lower protein levels in cancerous tissue compared to adjacent control tissue, which might be explained by the different protein translation efficiencies in cancer tissues." (PMID 34298614, 2021). "The established role of AKR1B10 in cancers via influencing important signaling pathways like the retinoid acid metabolism together with the here presented potential role in human eating behavior may give rise to further scenarios through which AKR1B10 may function in other pathways." (PMID 25887478, 2015).